MMP2 (matrix metallopeptidase 2)
Diseases named in the same sentence as MMP2 in open-access papers (continued):
Sharing a sentence is not in itself a finding about the gene and the disease.
oral squamous cell carcinoma (48 papers, 2003 to 2026). "Matrix metalloproteinase protein-2 (MMP-2) is linked to the human oral squamous cell carcinoma." (PMID 34393438, 2021). "MMP-2 is associated with metastasis of oral squamous cell carcinoma cells." (PMID 34112111, 2021). "Similarly, in a study of the association of the MMP2-1306 C>T polymorphism with the risk of oral squamous cell carcinoma (OSCC), Lin and colleagues reported that the CC genotype frequency was significantly higher in OSCC cases than in controls (P = 0.04)." (PMID 23637955, 2013). "In oral squamous cell carcinoma, luteolin administration influenced the cellular migration, invasion and lowered the p38 phosphorylation and MMP‐2 expression." (PMID 39830909, 2025). "Luteolin acts as an anti-metastatic agent by inhibiting the production of MMP-9 and MMP-2, while luteoloside regulates the expression of MMP-2 in human oral squamous cell carcinoma, including FaDu, HSC-3, and CA9-22, and inhibits cell migration and invasion." (PMID 39314630, 2024). "Analysis of tumor specimens from 12 patients with oral cavity squamous cell carcinoma suggested that MMP2 secreted from fibroblasts is involved in the invasion of oral cancer cells." (PMID 36677584, 2023). "Matrix metalloproteinase 2 (MMP-2) is involved in the destruction of periodontal tissue and the development of oral squamous cell carcinoma, and it also plays an important role in the destruction of dentin during the progression of caries." (PMID 35990090, 2022). "And miRNA-34c-5p has been shown to exert oncogenic effects in renal cell carcinoma, oral squamous cell carcinoma and other tumors by targeting MMP2 and TRIM29 to inhibit cell proliferation, invasive and migration." (PMID 36203485, 2022). "Calcium-dependent signaling can also induce MMP-2 expression in multiple cell types, including human periodontal fibroblasts and oral squamous cell carcinoma cells." (PMID 34094999, 2021). "In oral squamous cell carcinoma, fascin overexpression led to significant increase in cell migration, cell invasion, and MMP-2 activity with increased levels of phosphorylated Akt, ERK1/2 and JNK1/2." (PMID 29285273, 2017). "Oral squamous cell carcinoma (OSCC)-derived CAFs secrete CCL7 to up-regulate MMP2 expression by OSCC cells and thus increase cancer invasion." (PMID 26954362, 2016). "TGF-β was shown to induce the expression of MMP9 mRNA but decrease the expression of MMP2 mRNA by human oral squamous cell carcinoma cell lines." (PMID 25493076, 2014). "For example, shorter disease-free survival was noted in patients with oral squamous cell carcinoma (SCC) expressing higher MMP-2 enzymatic activity." (PMID 17311017, 2007). "The correlation of MMP-2 and P63 expression has been addressed in oral squamous cell carcinoma." (PMID 32582823, 2020). "Key words:Oral squamous cell carcinoma, MMP-2, MMP-8, immunohistochemistry." (PMID 26155333, 2015). "In oral squamous cell carcinoma, activities of MMP-2 and -9 correlate with disease-free survival." (PMID 12771921, 2003). "Within oral cavity SCC (OCSCC) specifically, high MMP2 expression is recognized as an independent prognostic biomarker." (PMID 40014866, 2025). "Previous studies have shown that PD reduces the expression of MMP2 and MMP9 to inhibit the invasion and metastasis of human oral squamous cell carcinoma." (PMID 36526799, 2023). "In Cal-27 and SCC4/9 cells derived oral squamous cell carcinoma, ECGC, and a MAPK-pathway inhibitor PD98059 diminished MMP2 activity and invasion/migration of these cells." (PMID 36677584, 2023). "Claudin-1 promotes the invasive ability of oral squamous cell carcinoma OSC-4 and NOS-2 cell lines through MT1-MMP and MMP-2 activation." (PMID 35280730, 2022). "PIX-GIT1 also modulates focal adhesion formation, invasion, and metastasis of oral squamous cell carcinoma via regulation of FAK, paxillin, ERK1/2, and MMP2/935." (PMID 35318302, 2022).
oral squamous cell carcinoma (continued). "EGCG can inhibit EGFR and MMP-2 phosphorylation, decrease MMP-2 activity and level, and enhance the anti-metastasis effect of gefitinib in the human oral squamous cell carcinoma cell, CAL-27." (PMID 31058847, 2019). "This present study was carried out to examine the immunohistochemical expression of MMP-2 and MMP-8 in oral squamous cell carcinoma cases seen at the Department of Oral Pathology, University College Hospital Ibadan." (PMID 26155333, 2015). "Furthermore, CEP55 drives the migration and invasion of oral cavity squamous cell carcinoma by increasing FOXM1 and MMP-2 activity." (PMID 37484531, 2023). "Moreover, MMP-2 and MMP-9 are overexpressed in the biopsy specimens of oral squamous cell carcinoma compared to the adjacent normal tissues." (PMID 32429564, 2020). "In addition, expression of CEP55 was correlated with aggressiveness of oral cavity squamous cell carcinoma by stimulating cell migration and invasion through increased FOXM1 and MMP-2 activity." (PMID 26615423, 2016). "Additionally, scutellarin may control the level of the transcription factor AP-1 to inhibit tumor angiogenesis in oral squamous cell carcinoma(OSCC), which is accomplished by decreasing the MMP-9 and MMP-2 levels, alongside decreasing integrin αvβ6 levels regarding human tongue cancer SAS cells." (PMID 38611849, 2024).
endometrial cancer (46 papers, 2007 to 2025). Primary or metastatic malignant neoplasm involving the endometrium (mucous membrane that lines the endometrial cavity). "Endometrial cancer progression has also been associated with increased expression of MMP-2 and MMP-9." (PMID 36982551, 2023). "High expression of both MMP-2 and 9, which was observed in endometrial carcinomas, was associated with parameters of tumor aggressiveness, including advanced stage, metastasis, and lymphovascular invasion." (PMID 33172126, 2020). "In aggregate, our data demonstrate that MMP-2 is closely associated with the pathways of the MAPKs involved in the GnRH-II-induced cell migration and invasion of endometrial cancer cells." (PMID 23786715, 2013). "Their results indicated that MMP-2 was expressed in a high percentage of tissues of patients with endometrial cancer and that its expression may be closely associated with the clinical stage, tumor invasion, and metastasis." (PMID 33287452, 2020). "Upregulated SPOCK2 in endometrial cancer can suppress tumor cell invasion and migration by modulating MMP2 activation." (PMID 40375334, 2025). "In some studies, it was found that in endometrial cancer, a high expression of MMP-2 and a low expression of TIMP-2 are important tumor markers." (PMID 38255200, 2024). "Regulating MMP2/1 (Matrix Metalloproteinase 2/1) can promote the proliferation and invasion of endometrial cancer cells." (PMID 38782818, 2024). "In endometrial cancer, the overexpression of MMP-2 protein is related to the depth of myometrial invasion as well as histologic grade and FIGO (International Federation of Gynecology and Obstetrics) stage." (PMID 36982551, 2023). "High expression of MMP-2 in combination with low expression of TIMP2 represents a high risk for local and distant metastasis of endometrial cancer." (PMID 36982551, 2023). "Previous study has shown that SOE inhibited dose-dependently the expression of MMP-9, MMP-2 and u-PA in endometrial cancer RL95-2 cells, thereby inhibiting migration and invasion." (PMID 35890125, 2022). "We have revealed that silencing of ZEB2 can effectively make endometrial cancer cells more sensitive to Paclitaxel treatment and lead to the downregulation of Twist1, MMP2, and vimentin and upregulation of E-cadherin." (PMID 35992812, 2022). "He found that STMN1 promotes the growth and invasion of endometrial carcinoma by mediating the secretion and activation of MMP2 and MMP9 proteins." (PMID 35126478, 2022). "According to in vitro studies, curcumin can prevent invasion and migration of endometrial carcinoma (EC) cell and plays an anti-metastatic role due to a reduction in the production and fuction of matrix metalloproteinases-2 and -9 (MMP-2 and MMP-9)." (PMID 33148295, 2020). "After treatment with the ERK signaling pathway inhibitor U0126, invasion of endometrial carcinoma cells and expression of MMP-2/-9 were also inhibited." (PMID 32083122, 2019). "The results indicated that RUNX1 promotes distant metastasis in endometrial carcinoma at least partially dependent on the regulation of MMP-2 and MMP-9 expression." (PMID 29391048, 2018). "Long non-coding RNA BANCR promotes endometrial cancer cell proliferation and invasion by regulating MMP2 and MMP1 via ERK/MAPK signaling pathway." (PMID 28199978, 2017). "In the present study, we demonstrated that GnRH-II promotes the cell migration and invasion of endometrial cancer cells through the increased expression and proteolytic activity of MMP-2, which specifically degrades the basement membrane." (PMID 23786715, 2013). "Targeting MMP-2 with an MMP-2 inhibitor blocked the GnRH-II-induced cell migration and invasion, indicating that the effects of GnRH-II in endometrial cancer cells are strongly correlated with MMP-2 expression." (PMID 23786715, 2013). "The transfection of the emmprin siRNA caused significant decreases in the expression of VEGF, MMP-2 and MMP-9 in endometrial cancer cells." (PMID 22640183, 2012).
endometrial cancer (continued). "In endometrial cancer, a high expression of MMP-2 and low expression of TIMP-2 seem to be potent markers for tumors, which provide a high risk of local and distant metastasis." (PMID 20942921, 2010). "In our study MMP-2 mRNA as well as MMP-2 protein was found in all three endometrial cancer cell lines." (PMID 20942921, 2010). "Interestingly, a systematic review and meta-analysis of 20 studies confirmed that overexpression of MMP2 is a predictive factor for the poor prognosis of endometrial cancer." (PMID 38731868, 2024). "MMP2 (Matrix Metalloproteinase 2) serum protein levels are elevated in endometrial cancer patients." (PMID 38782818, 2024). "SPOCK2 regulates endometrial cancer cells by targeting MMP2." (PMID 35342412, 2022). "They concluded that an indication of MMP-2 overexpression may be a predictive factor for the poor prognosis of patients diagnosed with endometrial cancer." (PMID 33287452, 2020). "Combined with the findings of this study, curcumin may downregulate the phosphorylation level of ERK/c-Jun and reduce the synthesis of AP-1, thereby reducing the transcription level of MMP-2/-9 and the invasion of endometrial carcinoma cells." (PMID 32083122, 2019). "MMP-2 and MMP-9 have been found to be associated with invasive endometrial cancers." (PMID 29391048, 2018). "Furthermore, MMP-2 enzymatic activity was measured by gelatin zymography using conditioned medium from endometrial cancer cells." (PMID 23786715, 2013). "A meta-analysis study showed MMP-2 to be closely associated with clinical stage, tumor invasion and metastasis indicating that overexpression of MMP-2 may serve as a poor prognostic factor for patients with endometrial cancer." (PMID 34830354, 2021). "Decreased expression of pro-MMP-9, pro-MMP-2 and MMP-2 in endometrial cancer cell lines after in vitro administration of medroxy progesterone acetate, an synthetic progesterone preparation, suggests that ECM remodelling could well be controlled by P4 as well as by LH in the CL tissue." (PMID 21291521, 2011). "Migration and invasion properties of endometrial cancer cells are provided via upregulating, among others, cyclooxygenase-2 (COX2) and matrix metalloproteinase 2 (MMP2)." (PMID 39188680, 2024). "Taken together, our results constructed a circ_0007534/miR-625/ZEB2 signaling, which drives endometrial cancer progression and chemoresistance by modulating several key EMT-related genes, including Twist1, MMP2, E-cadherin, and Vimentin." (PMID 35992812, 2022). "An increasing expression of MMP-2 and decreasing expression of TIMP-2 in endometrial carcinoma tissue correlates with the histological grade of endometrial carcinoma." (PMID 34830354, 2021). "Curcumin has also been reported to reduce the invasion of endometrial carcinoma cells by inhibiting the phosphorylation of ERK1/2 and downregulating the expression of MMP-2/-9." (PMID 32083122, 2019). "In this study, the overexpression of miR-302a-5p/367-3p or knockdown of HMGA2 in endometrial cancer cells decreased the expression of EMT-related proteins, such as MMP-2, MMP-9, Snail, Slug and N-cadherin, while increasing the expression of E-cadherin." (PMID 29391048, 2018). "Taken together with the previous results, the cell migration and invasion in endometrial cancer is regulated by the activation of the ERK1/2 and JNK signaling pathways by GnRH-II and is accompanied by the induction of MMP-2." (PMID 23786715, 2013). "Our study indicates that GnRH-II agonist promoted cell motility of endometrial cancer cells through the GnRH-I receptor via the phosphorylation of ERK1/2 and JNK, and the subsequent, MAPK-dependent activation of MMP-2." (PMID 23786715, 2013). "The level expression of MMP-2, MMP-14 and TIMP-2 in EN-1078D cell line is consistent with an endometrial cancer with high invasive potential." (PMID 17894888, 2007).
endometrial cancer (continued). "In endometrial cancer, CAFs activated PI3K/AKT and MAPK/ERK signals in a paracrine-dependent manner, or increased MMP-2 and MMP-9 secretion in an autocrine-dependent manner through CXCL12-CXCR4 axis, thus promoting the invasion and metastasis of endometrial cancer." (PMID 37497001, 2023). "In addition, overexpression of lncRNA TDRG1 promotes the viability, invasion and migration of endometrial cancer cells, inhibits cell apoptosis, and upregulates the expression of VEGF-A, PI3K, Bcl-2, MMP2 and surviving." (PMID 36338699, 2022). "In addition, isorhamnetin affected the expression of MMP2 and MMP9-related proteins and eventually inhibited the metastasis of human endometrial cancer Ishikawa cells." (PMID 36360027, 2022). "MMP-2 and TIMP-2 expression were found to be useful as potential markers for endometrial cancer." (PMID 34830354, 2021). "To further explore the mechanism underlying the effect of TMEFF1 on the invasion and migration of endometrial carcinoma cells, we used western blot to determine the changes in the key EMT proteins E-cadherin, Vimentin, MMP2, and MMP9 between before and after TMEFF1 knockdown." (PMID 34475991, 2021). "After overexpressed of miR-490-3p in endometrial cancer cells the expression of TGFα was decreased, while EGFR and the downstream related genes including NF-kB, MMP-2, Cyclin D1, survivin were decreased in mRNA and protein level, while increased Bax expression." (PMID 26843615, 2016). "A more important observation was that the GnRH-II-induced cell migration and invasion were abolished in cells pretreated with the MMP-2 inhibitor, indicating that MMP-2 was critical for the effects of GnRH-II on the cell migration and invasion of endometrial cancer cells." (PMID 23786715, 2013). "In this study, we used RT-PCR assays to examine whether VEGF, MMP-2 and MMP-9 were affected in endometrial cancer cells after transfection of the emmprin siRNA." (PMID 22640183, 2012). "Overall, the inhibition caused by the emmprin siRNA affected cell proliferation, migration and invasion through TGF-β, EGF, NF-κB, VEGF, MMP-2 and MMP-9 expression, which in turn resulted in increased levels of E-cadherin and reduced levels of Vimentin and Snail in endometrial cancer." (PMID 22640183, 2012). "Emmprin knockdown by the siRNA led to cell proliferation, migration and invasion through TGF-β, EGF, NF-κB, VEGF, MMP-2, and MMP-9 expression, which in turn resulted in increased levels of E-cadherin and reduced levels of Vimentin and Snail in endometrial cancer." (PMID 22640183, 2012). "Previous studies have shown increased expression of MMP-2 and MMP-9 in pre- and postmenopausal patients with polyps, suggesting that their expression could depend on the hormonal status of patients with endometrial polyps and type I endometrial cancer." (PMID 36982551, 2023). "Given that this cell line express constitutive levels of MMP-2 and MMP-14, and that EN-1078D cells were highly invasive in vitro, this cell line represent an important tool for the characterization and the study of the molecular and cellular mechanisms regulating endometrial carcinoma cell invasion." (PMID 17894888, 2007).